PLAC9 (placenta associated 9)
Tractability: Antibody: UniProt places it where antibodies can reach, with high confidence; UniProt predicts a signal peptide or a membrane-spanning region; its Gene Ontology location is reachable by antibodies, with medium confidence.
Gene: Protein-coding gene on chromosome 10 (80,131,682 to 80,145,359, forward strand). Ensembl gene ENSG00000189129.
Subcellular location: Secreted
Gene Ontology:
Molecular function: protein binding
Cellular component: extracellular region
Genetic constraint (gnomAD): Loss-of-function variants: 11 observed, 10.68 expected, observed/expected ratio (o/e) 1.03, 90% interval 0.65 to 1.67. The upper end of that interval is the gene's LOEUF score, 1.67, which puts it in group 6 of 6, group 1 being the genes least tolerant of losing a copy. Missense variants: 132 observed, 123.11 expected, observed/expected ratio (o/e) 1.07, 90% interval 0.93 to 1.24. Synonymous variants: 61 observed, 55.15 expected, observed/expected ratio (o/e) 1.11, 90% interval 0.9 to 1.37.
Homologues: Orthologues: chimpanzee PLAC9 (98% identical), macaque PLAC9 (96% identical), dog PLAC9 (76% identical), mouse Plac9 (73% identical), rat Plac9 (73% identical), guinea pig Plac9 (69% identical), pig PLAC9 (62% identical).
Diseases named in the same sentence as PLAC9 in open-access papers:
PLAC9 is named in the same sentence as 8 diseases in open-access papers, as found by Europe PMC text mining. Sharing a sentence is not in itself a finding about the gene and the disease. The quoted sentences say what the papers report.
lung adenocarcinoma (2 papers, 2021 to 2022). A carcinoma that arises from the lung and is characterized by the presence of malignant glandular epithelial cells. "First, we observed decreased expression of PLAC9 in various LCs, especially lung adenocarcinoma, in samples compiled in a publicly available database." (PMID 34123785, 2021). "We observed that in three previously published LC cohorts, the expression of PLAC9 was significantly decreased in lung adenocarcinoma compared to paired adjacent normal tissues, implicating a role of PLAC9 in lung epithelial pathogenesis." (PMID 34123785, 2021). "Bioinformatics analyses revealed that PLAC9 is repressed in lung cancers (LCs), especially lung adenocarcinomas, compared to that in the paired adjacent normal tissues, indicating that PLAC9 might be involved in the pathogenesis of pulmonary diseases." (PMID 34123785, 2021). "This suggested that LINC02126 may play important roles in the development of lung adenocarcinoma by regulating the expression of DCN, COX7A1, PLAC9, LUM and MFAP4." (PMID 36357869, 2022). "COX7A1, PLAC9 and LUM are up-regulated in lung adenocarcinoma." (PMID 36357869, 2022).
lung carcinoma (2 papers, 2021 to 2023). "To investigate the role of PLAC9 in LC, we evaluated the mRNA expression levels of PLAC9 in several of lung carcinoma cell lines, including NCI-H1299, A549, H1688, 95-D, MRC-5 as well as in the human bronchial epithelial cell line 16HBE." (PMID 34123785, 2021). "The expression level of PLAC9 mRNA in 16HBE cells was significantly higher than that in the lung cancer cell lines NCI-H1299, A549, H1688, and 95-D." (PMID 34123785, 2021). "To investigate whether PLAC9 plays a role in lung epithelial cell function and pathology, we analyzed PLAC9 expression levels in lung cancer using various publicly available databases and found reduced PLAC9 expression in lung cancer." (PMID 34123785, 2021).
atherosclerosis (1 paper, 2014). A disease characterized by the build-up of fatty material and calcium deposition in the arterial wall resulting in partial or complete occlusion of the arterial lumen. "Microarray data showed Dynlrb1 and Plac9 have lower expression in 129 compared to DBA and B6, although their association with atherosclerosis has not been reported." (PMID 24586312, 2014).
hepatoma (1 paper, 2018). "The expression level of Plac9 was higher in the primary liver carcinoma cell line PLC relative to human hepatoma cells SK-HEP-1, SMMC-7721, Lm3 and the normal liver cell line QSG-7701; moreover, in HEP-G2 cells and the human embryonic liver cell line L02, Plac9 expression was almost undetectable." (PMID 30291214, 2018).
pulmonary diseases (1 paper, 2021). "To investigate the potential role of PLAC9 in the abnormal reprogramming of airway epithelial cells (AECs), a key cause of pulmonary diseases, we constructed a stable PLAC9-overexpressing human bronchial epithelial cell line (16HBE-GFP-Plac9)." (PMID 34123785, 2021). "Our findings suggest that PLAC9 may be involved in lung diseases by regulating cell proliferation and migration." (PMID 34123785, 2021).
tumor (3 papers, 2016 to 2021). "The negative effect of PLAC9 on cell cycle progression suggests that PLAC9 may be a potential tumor suppressor." (PMID 34123785, 2021). "Similarly, PLAC9 was downregulated in most tumor types, except for KIRC and LIHC." (PMID 26655252, 2016). "In particular, survivorship analysis of early LUAD tumor regression candidates at the stage 1–2 interface (e.g., DAPK2 and PLAC9) revealed these genes to serve as positive LUAD prognosis markers." (PMID 34940617, 2021). "As a whole, the predictions made by sPLS-DA aligned well with the associated survivability for each tested gene, especially at early LUAD stage-stage interfaces, such as the LUAD tumor stage 1–2 interface, which includes DAPK2 and PLAC9." (PMID 34940617, 2021). "Interestingly, of the few genes that, via sPLS-DA, were predicted to contribute to tumor regression at certain stage-to-stage interfaces—including DAPK2, PLAC9, ABCB9, MELTF, CTHRC1, and OCIAD2, testing for LUAD patient survivability via AK4 combination resulted in a negative prognosis." (PMID 34940617, 2021). "More than half of the genes were not DE in any tumor type, while seven genes (C7, ADH1B, HSPB6, FXYD1, PLAC9, TMEM132A and ASF1B) were DE in all tumor types." (PMID 26655252, 2016).
PLAC9 also shares sentences with these, for which no sentence is quoted: infection (2 papers); bladder cancer (1).